CD44 (CD44 molecule (IN blood group))
Diseases named in the same sentence as CD44 in open-access papers (continued):
Sharing a sentence is not in itself a finding about the gene and the disease.
cancer (continued). "Therefore, we assume that the inducible acquisition of CD44 and its alternative splicing may play an important role in cancer cell resistance to PI3Kα inhibition." (PMID 33024087, 2020). "The short CD44 protein, lacking all alternative exons, is predominantly expressed in normal tissues, whereas CD44 variants containing exons v5, v6 and v7, are over-expressed in various cancers and associated to metastasis." (PMID 33287867, 2020). "Similarly, in recent systematic analysis of 1201 patients with advanced carcinomas selected from fifteen studies, CD44 expression was linked only to worse OS and not to DFS, RFS, or PFS." (PMID 32326107, 2020). "CD44 expression correlated negatively with MME (Pearson correlation coefficient (PCC) = 0.1242, p = 0.0091), suggesting that higher CD44 mRNA may be associated with either more primitive and/or dedifferentiated carcinomas." (PMID 32245446, 2020). "One explanation for this mechanism may involve the function of a cancer stem cell marker, CD44." (PMID 30781816, 2019). "Elucidating the cross-relation between the YAP nuclear localization and CD133+/CD44+ cells in the form of stiffer and softer matrix studies will improve the understanding in the regulatory mechanisms of CSCs and provide insight in the origin of cancer through Yamanaka factors." (PMID 31337825, 2019). "CD44, a stem cell marker, was also elevated in cancer tissues with upregulated expression of Musashi1, and there was a positive association between them, suggesting that Musashi1 may serve a crucial role in the maintenance of the self-renewal capacity of HCC cells." (PMID 31888604, 2019). "Thus, several anti-CD44 monoclonal Abs have been obtained with very promising results, since some of them selectively eliminate the self-renewal properties of CSCs in several malignancies and cancer cell lines." (PMID 31921125, 2019). "According to these findings we can conclude that the conflicting effects of CD44 on cancer cell properties are, at least partly, due to microenvironmental factors such as composition of the matrix, genetic background of cancer cells, ER status and cancer origin." (PMID 30909497, 2019). "A cancer-associated Microrchidia family CW-type zinc finger 2 (MORC2) (M276I) mutant was reported to promote metastatic ability of TNBC cancer cells by enhancing interaction with hnRNPM and splicing switch of CD44 from the epithelial isoform (CD44v) to the mesenchymal isoform (CD44s)." (PMID 31737791, 2019). "However, findings of increased soluble CD44 (sCD44) in patients with aggressive cancers suggest that additional post-translational modifications, such as proteolytic processing, may play essential roles in CD44’s mechanism of action." (PMID 31394726, 2019). "Therefore, FITC-HA-BSA NPs were selectively targeted to the CD44 receptor of ovarian SKOV3 cancer cells (CD44+) but not to CD44-deficient A2780 cells." (PMID 31060303, 2019). "Furthermore, to explore the functions of TGIF1 in regulating cancer stem cell (CSC) properties, we compared the expression levels of stemness transcriptional factors, such as Sox2, Nanog, CD44, Nestin, and CD133, between the TGIF1-deficient PDAC cells and TGIF1-sufficient PDAC cells." (PMID 31109321, 2019). "CD44 is an adhesive molecule that binds with extracellular matrices such as hyaluronic acid and is strongly involved in lymphocyte homing, lymphocyte activation, cell-to-cell adhesion, cell-to-matrix adhesion, and cell movement, as well as cancer cell proliferation and metastasis." (PMID 30478679, 2019). "Interestingly, increased autophagy enables cancer cells to upregulate CD44 expression." (PMID 30631039, 2019).
cancer (continued). "To understand the regulation of cancer immune evasion and help further studies to develop improved immune-based therapeutic strategies, we also explored the relationship between this stratification and CD44+/CD133+ CSCs existence and determined their prognostic significance." (PMID 30991694, 2019). "Moreover, P5–24 showed the expression of CD44, which is known as a common cancer stem cell marker." (PMID 31726709, 2019). "Therefore, the HA-modified LAP nanodisks with high drug loading efficiency, pH-sensitive drug release properties and CD44 targetability might be an efficient nanoplatform for cancer chemotherapy." (PMID 30960121, 2019). "However, the prognostic power of CD44 and CD44v in advanced cancer remains controversial." (PMID 30788285, 2019). "Mechanistically, serglycin can activate several cancer-associated signaling pathways in other types of cancer, including mitogen-activated protein kinase (MAPK)/β-catenin signaling, transforming growth factor-β2 (TGF-β2) signaling via interaction with CD44, and the NF-κB pathway." (PMID 30297672, 2018). "CD44, a non-kinase transmembrane glycoprotein, is overexpressed in several cell types including cancer stem cells and frequently shows alternative spliced variants that are thought to play a role in cancer development and progression." (PMID 29747682, 2018). "Interestingly, recent study showed that Lmc2 protein could interact with CD44 on cancer cell membrane, which indicated that during the process of IRI, laminin 5 might function as a ligand of CD44." (PMID 29632486, 2018). "In addition, we support that CD44 may be an important source of cancer neoantigens, most likely resulting from altered splicing and/or glycosylation." (PMID 29983670, 2018). "Interestingly, both peaks were insensitive to the CD44 knockdown in cancer cells." (PMID 29674746, 2018). "In addition, luminal A cancers include has the highest ratio of grade 2 tumors enriched in CD44." (PMID 30559934, 2018). "CD44 mediates multiple signaling pathways including protein kinases, cytoskeletal changes, intracellular pathways, proteinases, and transcriptional factors to contribute cancer cell division, proliferation, invasion, and angiogenesis as well as metabolic shift." (PMID 29747682, 2018). "Thus, HT is a robust CD44-independent anti-oxidant in cancer cells." (PMID 29674746, 2018). "CD44 variant isoforms including CD44v9 mitigate ROS, which may explain the high level of expression of CD44v9 in addition to S100P and COX-2 predominantly in the tissues of OV-CCA, a cancer driven by inflammation." (PMID 30402042, 2018). "However, the surviving tumors from these mice were enriched in CD44+/CD117+ cancer stem cells." (PMID 30231564, 2018). "Since, EMT is exploited by cancer cells to increase self-renewal and migration through a process that favors the emergence of CSCs7,9, we further evaluated the cytotoxic effect of 5FU+ Silibinin on these characteristic features of CD44+ subpopulation of HCT116." (PMID 30451890, 2018). "Notably, ICG-001 treatment significantly reduced metastasis of CD44+CD24highCD29+ (P < 0.0001, two-tailed t test) and unsorted cells (P < 0.0001, two-tailed t test), consistent with its proposed role in targeting β-catenin activity in immature cancer cells." (PMID 30029671, 2018). "However, when we treated cancer cells with the combination, CD44 expression was abolished." (PMID 30250641, 2018). "Therefore, the glycoclusters strategy could have tremendous potential in gene silencing applications in all CD44 overexpressing cancer cells." (PMID 29899207, 2018). "The different interactions with CD44, binding affinities and receptor clustering and different conformations of HA may help explain the varying effects of different molecular weights of HA in normal and cancer cell biology." (PMID 30513961, 2018). "Notably, our data show that CD44 also interacts with IL-13Rα2, which may account for the function of IL-13Rα2 in cancer metastasis." (PMID 30165890, 2018).
cancer (continued). "Furthermore, CD44 was reported as a promising cancer stem cell (CSC) marker in canine PC." (PMID 29894516, 2018). "In addition to EpCAM, Dt81Hepa1-6 cells express both CD24 and CD44 (data not shown), two markers of increased tumorigenicity that have also been associated with cancer stem cells." (PMID 28152020, 2017). "However, the relationship between CD44 expression and the stemness of cancer cells is unclear." (PMID 28460475, 2017). "Finally, CD44 antigen appeared in the “Proteoglycans in Cancer” and “ECM-Receptor Interaction”." (PMID 28697756, 2017). "Thus, the CD44 functions are also exploited in diverse pathologies, such as cancer." (PMID 29062810, 2017). "Furthermore, CD44 is an important cancer stem cell (CSC) surface marker." (PMID 29371972, 2017). "However, the question of whether HA displays any effect on CD44+CD24−/low cancer stem cells is presently unknown." (PMID 28837080, 2017). "Apparently, CD44 may be a crucial molecule contributing to refractive cancer." (PMID 28515423, 2017). "With regard to the CAF model, patient-derived normal and according cancer-associated fibroblasts revealed a conserved gene expression, defined by increased transcript levels of ACTA2, COL1A1, TNC, VEGFA and ALDH1A3, with concomitant decreased expression of CAV1, CD44 and VIM in CAFs." (PMID 28372546, 2017). "Furthermore, we confirmed that these CD133+ cancer cells were CSCs, which co-express TF and CD44." (PMID 27903969, 2017). "Thus, CD44 is thought to be a biomarker for cancer stem cells (CSCs)." (PMID 28279210, 2017). "In this study, we identified a set of associated DEGs (CD44, CTGF, DPP4, CRYAB, EGLN3, FGF1, and FOS) with at least one functional enrichment, such as “angiogenesis”, “binding of endothelial cells”, “development of blood vessel”, MAPK signaling, HCM, and pathways in cancer." (PMID 28623314, 2017). "However, these are only examples for the role of CD44 in cancer." (PMID 29062810, 2017). "Therefore, an understanding of the binding mechanism of CD44 to cancer cells may aid in the design of effective DDS therapeutic techniques for cancer patients." (PMID 28230204, 2017). "However, stemness concomitant with EMT could also be considered as the emergence or increase of cancer stem cells (CSCs), which have enhanced tumorigenicity, partial stemness as in self-renewal and differentiation, and CD44+/CD24-/low on cell surface." (PMID 27258544, 2016). "In addition, we investigated whether expression of CD44 and CD166 was associated with cancer cell invasiveness." (PMID 27494849, 2016). "In conclusion, our meta-analysis demonstrates that CD44 polymorphisms may not represent risk factors for cancer." (PMID 27738347, 2016). "In addition, EFNB1 and NGFR were downregulated in CD44+ cancer cells versus normal cells." (PMID 26673618, 2016). "Finally, Dr Orian-Rousseau speculates on the function of CD44 in cancer stem cells (CSCs), which has so far has been studied as a biomarker for these cells, but its role in CSCs remains elusive." (PMID 26904028, 2016). "Similarly, metformin is shown to preferentially target CD44 + cancer stem cells for chemotherapy." (PMID 27381673, 2016). "In this study, we found that HCC patients with different CSC markers (CD133, CD90, CD13, CD24 or CD44) possessed distinct clinic-pathological features, suggesting that these cells with different cancer stem cell markers may be present in an identical HCC population." (PMID 26735577, 2016). "To determine whether change in the proportion of CD44+/CD24− cells induced by the co-culture of macrophages with apoptotic MCF-7 cells influence the malignancy of these cancer cells we tested the tumorigenicity of the MCF-7 cells exposed to the conditioned media using the nude mice model." (PMID 26016502, 2015).
cancer (continued). "Analysis of cancer-initiating cell CD44 and CD133 subsets revealed drug-dependent responses of CD26/CD44/CD133 populations, suggesting that the benefits of combining standard chemotherapies 5-fluoruracil and oxaliplatin may be derived from their complementary elimination of cell populations." (PMID 26552750, 2015). "Thus, the ability of the cancer cell to produce such a pericellular matrix, requiring CD44, HA, and versican (or aggrecan), could add to the chances of survival in the circulation." (PMID 26539408, 2015). "Thus, we hypothesized that CD44 may contribute to cell cycle regulation to promote cancer cell proliferation." (PMID 25605020, 2015). "For all these reasons, targeting CD44 may be a successful approach in cancer therapy." (PMID 26569327, 2015). "Thus, CSCs and other CD44-expressing cancer cells may reduce oxidative stress through a variety of mechanisms." (PMID 26322272, 2015). "The observation that blood glucose clearance was reduced in CD44-deficient mice, whereas CD44-deficient mice display relative resistance to T1D, encouraged us to ask whether glucose uptake by peripheral cells and β cells is a CD44-dependent event, as it has been shown for cancer cells." (PMID 26624007, 2015). "However, a picture has emerged suggesting that CD44 may function differently at different stages of cancer progression." (PMID 25999946, 2015). "However, some data indicate less intensive expression of the CD44 in cancer cells." (PMID 25129125, 2015). "Thus, targeting drugs to CD44 are one of the appropriate strategies for cancer treatment." (PMID 26448753, 2015). "However, it is uncertain whether the 350-nm grating induces the expression of CD44 or if it is able to isolate the cancer stem cell-like population in MCF7." (PMID 25905435, 2015). "This may indicate that CD44 can promote cancer cell proliferation." (PMID 25605020, 2015). "Thus, a better understanding of the molecular mechanisms involved in HA and CD44 control of CSC stemness may help in the design of more effective therapies for cancer patients." (PMID 26322272, 2015). "In addition, CD44 is also expressed in various types of cancer cells and cancer stem cells." (PMID 26124179, 2015). "The contrasting results observed in Du145 and LAPC9 models with respect to the tumorigenicity of CD44+α2β1+ cells suggest that the ability of combinatorial marker-sorting strategy to further enrich CSCs over single marker strategies is dependent on the cancer model analyzed." (PMID 26246472, 2015). "Interestingly, TGFβ1 could also up-regulate cancer stem-like cell marker CD44 expression (via Western blot assay)." (PMID 25483103, 2015). "Therefore, the wide expression of CD44 in normal tissues is a complicating factor in CD44 antibody-conjugated drug-induced toxic epidermal necrolysis and hematologic toxicity, thus making selective and safe antibody-based cancer therapy impossible." (PMID 25909172, 2015). "Therefore, the use of AR-42 may allow CD44 targeting in numerous cancers that may both overcome resistance to standard therapeutic agents, as well as open up new treatment directions focused on cellular adhesion." (PMID 26429859, 2015). "Furthermore, the properties of NPC CSCs were studied by treating NPC cells with rapamycin to determine whether inhibition of the mTOR signaling pathway would reduce the number of CD44-positive cells and depress cancer cell proliferation." (PMID 26202311, 2015). "Our findings suggest that combinations of inhibitors against AKT and CD44 could be used to avoid negative feed-back loops associated with AKT inhibitors which may cause the cancer cells to survive treatment." (PMID 24760019, 2014). "For this reason the cancer stem cell-like phenotype commonly observed in IBC tumors may contribute to their aggressive nature but also may offer itself novel therapeutic strategies to the selective targeting of CD44+/CD24− CSCs from bulk tumors." (PMID 24970653, 2014).
cancer (continued). "Furthermore, IWP-2 significantly reduced the cancer stem cell population in tamoxifen resistant cells, as confirmed by reduced capacity for mammosphere formation and a reduction in the percentage of CD44+CD24−/low cells." (PMID 24178749, 2014). "Interestingly, as predicated by TargetScan and previous study, miR-34a could negatively regulate different kinds of mRNAs including CD44 in some human cancers." (PMID 25551284, 2014). "Thus, as an analogy, it is plausible to suspect that exon v10 of CD44 expressed on cancer cells could play a key role in promoting metastasis by possibly mediating cell adhesion and migration at secondary sites." (PMID 24586375, 2014). "However, as CD44 is expressed in multiple isoforms, its role in cancer cells and senescent cells may be mediated by different isoforms." (PMID 25059316, 2014). "ALDH, like CD44, may also have a functional role in cancer progression." (PMID 24019906, 2013). "In most cancers, the dysregulated expression of CD44 is not the result of CD44 mutations." (PMID 23445749, 2013). "Given limited success from VEGF-targeting approaches and positive correlations between CD44 expression and enhanced angiogenic properties of cancer cells, the FKBPL peptide may prove advantageous in the field of novel anti-angiogenic agents currently in clinical use." (PMID 23457460, 2013). "However, studies on cancer cell lines showed substantial variation in CD44 and CD24 expression." (PMID 22693526, 2012). "Na+-H+ exchanger interacts with CD44 in lipid rafts and may regulate cancer cell migration." (PMID 22253629, 2012). "It is possible that Oct-4 may regulate cancer stem cell maker CD44 gene expression." (PMID 23185620, 2012). "Also the expression of the cancer stem cell marker CD44 is integrin-regulated, and it can be speculated that integrin-relayed signals are needed to maintain a cancer stem cell population." (PMID 21941547, 2012). "Besides interacting with CD44 and integrins expressed on neoplastic cell surface, OPN contributes to moulding the cancer-associated immunological microenvironment by directly inducing Ms recruitment and activation towards amplification of the inflammatory milieu rich in TNF, IL-1b, and IL-6." (PMID 22400028, 2012). "This can be attributed in part to the prominent spreading and adhesion of cancer cells mediated via specific HA-CD44 interactions, and may require both adhesion to the surface (grip) and successive cleavage of CD44 (release) during cell migration as suggested by a previous study." (PMID 22916191, 2012). "Targeting overexpressed CD44 in cancer cells may also control CaP progression." (PMID 20736947, 2010). "However, if ceramide is reduced, then peripheral cells may divide asymmetrically giving rise to self-renewing CD44+ and rapidly dividing CD44- cancer cells." (PMID 19087284, 2008). "Moreover, the obvious heterogeneity of cells with various CD44/CD24 expression within individual tumors may be indicative of a cancer stem cell subpopulation giving rise to more differentiated and committed cell populations." (PMID 18559090, 2008). "Thus, steps in the cascade of events required for the spread of cancer are dependent on distinct groups of genes, and the CD44+/CD24- phenotype may define the expression of the group of genes involved in invasion." (PMID 17062128, 2006). "Thus, distant metastasis in patients with elevated levels of CD44+/CD24- cells may be related to enhanced invasiveness of cancer cells." (PMID 17062128, 2006). "Hepatic Mif knockdown not only reduced the overall infiltration of TAMs and the number of CD44+CK19+ cancer cells, but TAMs existed in a more distant proximity to CD44+ cancer cells as compared to the control group." (PMID 41545340, 2026). "Mechanistically, loss of PAK1 promoted mRNA decay and inhibited the expression of CD44, SAA1, MTOR, RPS6KB1, and EIF4G1, the factors involved in tumorigenesis in many cancers." (PMID 41459112, 2026).